FGF21 (fibroblast growth factor 21)
Diseases named in the same sentence as FGF21 in open-access papers (continued):
Sharing a sentence is not in itself a finding about the gene and the disease.
Obesity (continued). "As a metabolic factor, FGF21 increases in type 2 diabetes and obesity patients, which might be a kind of compensation for insulin deficiency and one study confirmed that serum FGF21 increased before type 2 diabetes was diagnosed in women." (PMID 33995273, 2021). "Currently, FGF21 is considered an attractive therapeutic target to treat obesity and obesity-associated metabolic disorders, including non-alcoholic fatty liver disease (NAFLD)." (PMID 34943946, 2021). "Importantly, high serum FGF-21 is a predictor of obesity, insulin resistance, and metabolic syndrome." (PMID 34199607, 2021). "Given the insulin secretion stimulatory effect of BCAAs on β-cells, the high levels of BCAAs observed in obesity and T2DM may suggest a deleterious long-term effect or resistance to their function similar to what happens to FGF-21 in obesity." (PMID 33672162, 2021). "FGF21 signaling through KLB in WAT may be primarily related with obesity, as decreased KLB expression was observed in WAT of obese mice, non-human primates fed with high-fat diet, and obese subjects with different levels of abnormal glucose homeostasis." (PMID 34912302, 2021). "Several studies have reported elevated circulating FGF21 levels in rodent models of obesity." (PMID 35046901, 2021). "Based on numerous studies that demonstrate its broad and significant impact on systemic energy metabolism in response to various metabolic challenges, hepatokine FGF21 holds promise as a potential therapeutic for a wide range of metabolic abnormalities, including obesity and type 2 diabetes." (PMID 34944728, 2021). "The unidirectional beneficial effects of exogenous FGF21 on metabolism in male and female mice with dietary-induced obesity were accompanied by similar changes in the expression of certain genes in the liver and sex-specific changes in gene expression in adipose tissue." (PMID 34638898, 2021). "Indeed, fibroblast growth factor 21 (FGF21) is a master metabolic regulator that serves as an important paracrine signaling molecule with remarkable ability to reverse diabetes and obesity." (PMID 33664851, 2021). "Altered DNA methylation in promoters of transcription factor genes (PPARA, KLF15, NR3C1, RORA and ATF4) known to regulate FGF21 expression and its binding receptors and co-factors (FGFR1, FGFR3 and FGFRL1 and KLB) has been revealed in relation to the elevated levels of circulating FGF21 in obesity." (PMID 33670024, 2021). "However, taking into account the ISR-induced anti-obesity effects of FGF21 in addition to GDF15, ISR enhancers represent attractive alternatives for appetite control in patients with metabolic disorders." (PMID 34877504, 2021). "Pharmacological levels of FGF21 exert both anti-obesity and anti-inflammatory activities." (PMID 33668583, 2021). "Furthermore, it has been shown that FGF-21 shifts VLDL-TG uptake from white to brown adipose tissues in obesity." (PMID 33672162, 2021). "Insulin resistance and obesity affect the secretion of FGF21." (PMID 34912302, 2021). "Thus, to overcome the vicious circle of obesity, intervention approaches such as treadmill exercise, a change in diet or fasting are suitable and common methods to lower FGF21 concentration while increasing FGF21 sensitivity." (PMID 34578793, 2021). "Long-term recombinant FGF-21 therapy lowers hepatic and serum triglyceride levels and decreases the fattiness of the liver in mice with diet-induced obesity; these actions may occur through suppression of SREBP1, a lipogenic gene." (PMID 34206460, 2021). "Notably, the administration of recombinant FGF21 protein in various animal models of obesity consistently achieves therapeutic outcomes including weight loss, improved glucose tolerance/insulin resistance, increased energy expenditure, and reduced adiposity." (PMID 34074713, 2021).
Obesity (continued). "However, the relationship between FGF21 and various aging-related metabolic diseases has not yet been clarified; thus, in the following, we will focus on the relationship between FGF21 and obesity, T2DM, and NAFLD." (PMID 33869312, 2021). "In this process of energy homeostasis, FGF21 is involved by modulating the metabolism in healthy individuals as well as in obesity and could function as a putative biomarker for improved behaviour after weight reduction in obese mice." (PMID 34578793, 2021). "Recently, FGF21 has received great interest as it could also be involved in aging, dementia, and obesity-induced cognitive impairment." (PMID 35002679, 2021). "The stratification by BMI may explain why in our results, overweight/obesity groups had higher levels of FGF21 protein, particularly in the control group; however; the number of controls used in the study may be a limitation." (PMID 34019585, 2021). "The discrepancies between this study and the initial study that suggested that obesity is an FGF21-resistant state could potentially be explained by different functional readouts and doses of rFGF21 utilized." (PMID 35046901, 2021). "FGF-21 has been proposed as a therapeutic target in obesity and insulin resistance." (PMID 34822430, 2021). "Recent reports have indicated that small-molecule inhibitors of GSK3 have favorable metabolic effects in rodents, which exhibit some of the same metabolic effects as FGF21 administration, including improved glucose tolerance and prevention of diet-induced obesity." (PMID 32190098, 2020). "In addition to its associations with obesity and T2DM, FGF21 levels have also been associated with increased risk for CVD." (PMID 32158768, 2020). "Also fibroblast growth factor 21 (FGF21) has anti-inflammatory properties in obesity related inflammation and is observed to increase sensitivity to insulin." (PMID 32471255, 2020). "Moreover, higher FGF21 and GDF15 circulating levels are associated with age-related diseases such as obesity, cardiovascular disease, insulin resistance, type 2 diabetes, and neurodegeneration, as well as cancer cachexia." (PMID 33374852, 2020). "Given that FGF21 has been shown to be elevated in obesity, and in particular in subjects with insulin resistance, the notion that FGF21 levels would become even further elevated following RYGB surgery, a procedure which rapidly improves insulin sensitivity, represents a paradox." (PMID 32158768, 2020). "Elegant studies using tissue-specific Fgf21 KO mice show that adipocyte-derived Fgf21 is not involved in obesity-associated insulin resistance, and that adipose-derived Fgf21 doesn't circulate, instead acting in a paracrine fashion." (PMID 32158768, 2020). "The generation of UCP1/FGF21 double-knockout mice (dKO) fully reverses obesity resistance." (PMID 32005798, 2020). "Treatment of HepG2 and primary mouse hepatocytes with curcumin (2 μM) for 6 h resulted in significantly reduced fibroblast growth factor 21 (Fgf21) resistance, a hepatokine that is paradoxically found to be elevated with obesity and diabetes, while having attenuated action." (PMID 31906278, 2020). "On the other hand, the therapeutic role of FGF21 for obesity was evaluated in an animal study." (PMID 32210348, 2020). "FGF21 gene therapy has been demonstrated to be a potential therapy for obesity and type 2 diabetes." (PMID 32423100, 2020). "Obesity is characterized by a fibroblast growth factor 21 (FGF21)-resistant status and FGF21 production could be adjusted by some bioactive dietary compounds." (PMID 32650619, 2020). "Obesity increased plasma glucose and insulin and decreased irisin and FGF-21." (PMID 32230849, 2020). "The mRNA levels of JMJD3 and KLB were decreased, whereas those of Fgfr1 and Fgfr4 were increased, after feeding a HFD, suggesting that decreased expression of KLB may contribute to FGF21 resistance in obesity." (PMID 32042044, 2020).
Obesity (continued). "Although the role of FGF21 appears to be complex because FGF21 performs diverse metabolic functions in multiple target organs, the metabolic benefits provided by FGF21 may have pharmacological significance in improving obesity and insulin resistance." (PMID 32516922, 2020). "Although FGF21 has several beneficial effects on insulin sensitivity and glucose and lipid metabolism, circulating FGF21 levels are paradoxically increased in hepatosteatosis, obesity, and type 2 diabetes in rodents and humans." (PMID 33364514, 2020). "In male Ay-mice, the blockage ofMC4Rs does not prevent the anti-obesity effect of FGF21:its administration results in weight loss and blood insulindecrease." (PMID 33659800, 2020). "In male Ay-mice, the blockageof MC4Rs did not prevent anti-obesity effect of FGF21, andits administration resulted in weight loss and decreased bloodinsulin levels." (PMID 33659800, 2020). "As such, a clear role for adipocyte-derived FGF21 in obesity and associated metabolic syndrome is still lacking." (PMID 32158768, 2020). "Interestingly, it has been reported that serum FGF21 levels were high in people with obesity or metabolic syndrome." (PMID 32957703, 2020). "Furthermore, patients with obesity-related insulin resistance have an impaired FGF21 upregulation after exercise." (PMID 32604889, 2020). "Considering the fact that obesity, metabolic disorders, and estrogen imbalance are important factors in the pathogenesis of both breast and endometrial cancer, the potential involvement of FGF21 is also pointed out in endometrial cancer patients." (PMID 32570721, 2020). "Recently, studies have suggested that obesity is an FGF21 resistant state, suggesting that FGF21 may play a role in common forms of insulin resistance." (PMID 33210059, 2020). "The anti-obesity drug development pipeline focuses on multiple targets, including those that act by increasing metabolic rate, such as via the fibroblast growth factor 21 (FGF21) signaling pathway and browning of adipose tissue." (PMID 32630256, 2020). "Taken together, our findings provide evidence that during TRF, FGF21 may act as a critical player in modulating female fertility and provide novel insights into the dietary intervention on obesity or infertility interventions." (PMID 33135359, 2020). "Paradoxically, FGF21 levels increase in patients with obesity, which might represent a state of FGF21 resistance." (PMID 32604889, 2020). "The current research assesses the possibility of using FGF21 in the treatment of obesity." (PMID 30927227, 2019). "This may relate to species-specific differences in FGF21 signaling, or perhaps result from FGF21 resistance seen in obesity." (PMID 30802174, 2019). "Moreover, the increase in FGF21 level is induced by pathological physical stress conditions like obesity, anorexia nervosa, hypothermia, amino acid deprivation or malnutrition, and nephropathy." (PMID 31847236, 2019). "But in obesity patients, the serum FGF21 levels are elevated." (PMID 31548436, 2019). "Besides its physiological induction, FGF21 is also elevated in pathological conditions, such as obesity, insulin resistance, or liver diseases, and impairment in FGF21 signaling in these cases has also been also described." (PMID 31546675, 2019). "Moreover, it appears that obesity can lead to an FGF21-resistant state and that KLB expression is reduced in obese mice." (PMID 31548436, 2019). "We next investigated if disruption of the normal regulation of FGF21 in FGF21-overexpressing mice could interfere with the anti-obesity effect of loading." (PMID 30888399, 2019). "Weight loss may diminish obesity risk via regulation of adipose-tissue-derived factors, finally modulating concentrations of FGFs (FGF19, FGF21) and β-klotho co-receptor." (PMID 31151464, 2019). "However, some studies have shown that administrating FGF21 prevents diet-induced obesity and insulin resistance in mice and humans." (PMID 31057418, 2019).
Obesity (continued). "The liver appears to be the major source of FGF21 in the regulation of metabolic homeostasis in response to various nutritional conditions including fasting, consuming a ketogenic diet, steatosis, and obesity." (PMID 31408968, 2019). "This review describes the mechanisms by which FGF21 induces “browning” of adipose tissue and how it may have a role in the treatment of human metabolic diseases, including obesity and type 2 diabetes." (PMID 30804796, 2019). "Understanding how FGF21 works could therefore help researchers to develop new treatments for obesity and type II diabetes." (PMID 30688648, 2019). "Mouse studies have shown that high-fat diet-induced obesity leads to FGF21 blood level increase." (PMID 30927227, 2019). "The paradoxical increase in FGF21 levels in obesity and diabetes has been reported in many studies, leading to the hypothesis of a potential FGF21-resistant state." (PMID 31543863, 2019). "Previous studies reported that a methionine- and choline-deficient lean diet, and hepatocarcinogenesis, induced FGF21 expression in a manner independent of obesity and diabetic conditions." (PMID 31408968, 2019). "As a novel endocrine hormone, FGF21 has profound effects on the regulation of metabolic parameters such as glucose and lipid homeostasis, and represents a promising potential therapeutic target in type 2 diabetes (T2D) and obesity." (PMID 30691455, 2019). "Obese, diabetic mice, as well as people suffering from obesity, show elevated FGF21 levels." (PMID 30927227, 2019). "The present study findings are complementary to prior work, showing that FGF21 administration can improve glucose tolerance and insulin sensitivity in diabetic rodents as well as a prior study showing that transgenic overexpression of FGF21 is protective against HFD-induced obesity in mice." (PMID 31121855, 2019). "In addition, obesity has been validated to be a FGF21 resistance state, and that further studies on addressing FGF21 resistance are needed." (PMID 31498116, 2019). "Initially, FGF21 was described as a promising target to treat obesity and insulin resistance." (PMID 31546675, 2019). "Similarly, in some metabolic states such as obesity and diabetes, FGF21 levels are elevated and an FGF21-resistant condition has been suggested to also accompany these diseases." (PMID 31281288, 2019). "Circulating FGF21 levels are elevated in rodents and humans with obesity and T2DM." (PMID 31121855, 2019). "With the increase in metabolic syndrome patients, FGF21 could potentially be a revolutionary new way to treat obesity, T2D and other metabolic diseases." (PMID 30691455, 2019). "Moreover, Drp1 deficiency reduces fat mass, induces ER stress, and promotes energy expenditure through increasing the expression of FGF21 in the liver, which helps mice fed with a high-fat diet to be protected against obesity." (PMID 31551926, 2019). "Given that muscle dependent systemic release of FGF21 also increases with obesity and ER stress, we hypothesized that FGF21 has the potential to protect obesity-induced atrophic responses." (PMID 31312114, 2019). "To confirm whether the effect of FGF21 on obesity-induced skeletal muscle atrophy was related to AMPK, we investigated the AMPK phosphorylation by Western blotting." (PMID 31312114, 2019). "Given that pharmacological FGF21 treatment has the capacity to reduce fat mass, we next investigated if disruption of the normal regulation of FGF21 in FGF21-overexpressing mice could interfere with the anti-obesity effect of loading." (PMID 30888399, 2019). "Notably, SAT mass in FGF21KO mice was significantly lower than that in WT mice, but VAT mass was similar between WT and FGF21KO mice, suggesting that FGF21 is required for the accumulation of subcutaneous fat in diet-induced obesity." (PMID 29348470, 2018).
Obesity (continued). "Here, we took advantage of adeno‐associated viral (AAV) vectors and their ability to mediate multi‐year production of therapeutic proteins to develop a gene therapy strategy for obesity and T2D based on FGF21 gene transfer to the liver, adipose tissue, or skeletal muscle." (PMID 29987000, 2018). "FGF21 is shown to be protective against obesity and atherosclerosis." (PMID 30157856, 2018). "We first examined whether FGF21 is involved in the protective effects of CO against obesity-mediated metabolic syndrome." (PMID 29295856, 2018). "Pharmacological treatment with FGF21 ameliorates age‐related metabolic disorders such as insulin resistance, dyslipidemia, and obesity in rodents, and pilot studies in humans indicate that treatment with an FGF21‐analog has beneficial effects on hyperlipidemia and body weight." (PMID 30043445, 2018). "In humans, FGF21 serum levels correlate with obesity and importantly appear to reflect the degree of fatty infiltrations in the liver, suggesting that levels could serve as a marker for NAFLD." (PMID 30355361, 2018). "Our present results may explain an influence of DJOS surgery on the normalisation of the FGF21 sensitivity, which has been reported to be highly reduced under obesity conditions." (PMID 30211220, 2018). "Furthermore, in adipose tissue, others have reported decreased expression of the FGF21 receptor and/or its co-receptor KLB in diabetes and obesity, suggesting a state of FGF21 resistance." (PMID 29593555, 2018). "Currently, three members of the FGFs family have been linked to obesity: FGF1, FGF15/19 and FGF21." (PMID 29652901, 2018). "Fibroblast growth factor 21 (FGF21) is considered a promising therapeutic agent for T2D/obesity." (PMID 29987000, 2018). "Another potential explanation for the increased FGF-21 in obesity and IR is the existence of a FGF-21-resistant state, a hypothesis that has been proven in a diet-induced obesity mouse model." (PMID 29445355, 2018). "In light of this and in response to a recent call for a unified definition of “FGF21 resistance”4, I would like to discuss the controversy surrounding “FGF21 resistance” during obesity, highlight unresolved questions and outline additional criteria for its definition." (PMID 29983922, 2018). "The PPARα agonist–FGF21–WAT interaction may contribute to the anti-obesity effect of PPARα agonists." (PMID 30041488, 2018). "Likewise in humans, FGF-21 analogs have shown beneficial effects on body weight and glucose control in obesity and diabetes." (PMID 30298107, 2018). "The thermogenic functions in the iWAT and BAT of mice treated with pemafibrate were increased via increased hepatic FGF21 production and the direct effects of pemafibrate on PPARα in peripheral tissues, leading to the amelioration of obesity-induced dysfunction." (PMID 30041488, 2018). "Moreover, despite the metabolic health‐promoting effects of FGF21, the levels of this hormone are increased under conditions such as obesity and diabetes, an apparent incongruity that has been attributed to altered tissue responsiveness to FGF21." (PMID 30043445, 2018). "Finally, the hepatic fibroblast growth factor 21 (FGF21) enhances lipid oxidation and lipolysis, suppresses hepatic steatosis, and decreases obesity-induced insulin resistance." (PMID 30211220, 2018). "The potential of FGF21 to treat obesity and insulin resistance has prompted the pharmaceutical industry to develop a myriad of analogues and mimetics that have the same biological actions than endogenous FGF21 but improved pharmacokinetic properties." (PMID 29987000, 2018). "We propose that Fgf21 methylation represents a form of epigenetic memory that persists into adulthood, and it may have a role in the developmental programming of obesity." (PMID 29434210, 2018). "Similarly, liver‐specific overexpression of FGF21 in transgenic mice protects animals from diet‐induced obesity and insulin resistance." (PMID 29987000, 2018).